CDK5 (cyclin dependent kinase 5)
Description:
Proline-directed serine/threonine-protein kinase essential for neuronal cell cycle arrest and differentiation and may be involved in apoptotic cell death in neuronal diseases by triggering abortive cell cycle re-entry. Interacts with D1 and D3-type G1 cyclins. Regulates several neuronal development and physiological processes including neuronal survival, migration and differentiation, axonal and neurite growth, synaptogenesis, oligodendrocyte differentiation, synaptic plasticity and neurotransmission, by phosphorylating key proteins. Negatively regulates the CACNA1B/CAV2.2 -mediated Ca(2+) release probability at hippocampal neuronal soma and synaptic terminals (By similarity). Activated by interaction with CDK5R1 (p35) and CDK5R2 (p39), especially in postmitotic neurons, and promotes CDK5R1 (p35) expression in an autostimulation loop. Phosphorylates many downstream substrates such as Rho and Ras family small GTPases (e.g. PAK1, RAC1, RHOA, CDC42) or microtubule-binding proteins (e.g. MAPT/TAU, MAP2, MAP1B), and modulates actin dynamics to regulate neurite growth and/or spine morphogenesis. Also phosphorylates exocytosis associated proteins such as MCAM/MUC18, SEPT5, SYN1, and CDK16/PCTAIRE1 as well as endocytosis associated proteins such as DNM1, AMPH and SYNJ1 at synaptic terminals. In the mature central nervous system (CNS), regulates neurotransmitter movements by phosphorylating substrates associated with neurotransmitter release and synapse plasticity; synaptic vesicle exocytosis, vesicles fusion with the presynaptic membrane, and endocytosis. Promotes cell survival by activating anti-apoptotic proteins BCL2 and STAT3, and negatively regulating of JNK3/MAPK10 activity. Phosphorylation of p35/CDK5R1 enhances its stabilization by preventing calpain-mediated proteolysis producing p25/CDK5R1 and avoiding ubiquitin ligase-mediated proteasomal degradation. During aberrant cell-cycle activity and DNA damage, p25/CDK5 activity elicits cell-cycle activity and double-strand DNA breaks that precedes neuronal death by deregulating HDAC1. DNA damage triggered phosphorylation of huntingtin/HTT in nuclei of neurons protects neurons against polyglutamine expansion as well as DNA damage mediated toxicity. Phosphorylation of PXN reduces its interaction with PTK2/FAK1 in matrix-cell focal adhesions (MCFA) during oligodendrocytes (OLs) differentiation. Negative regulator of Wnt/beta-catenin signaling pathway. Activator of the GAIT (IFN-gamma-activated inhibitor of translation) pathway, which suppresses expression of a post-transcriptional regulon of proinflammatory genes in myeloid cells; phosphorylates the linker domain of glutamyl-prolyl tRNA synthetase (EPRS) in a IFN-gamma-dependent manner, the initial event in assembly of the GAIT complex. Phosphorylation of SH3GLB1 is required for autophagy induction in starved neurons. Phosphorylation of TONEBP/NFAT5 in response to osmotic stress mediates its rapid nuclear localization. MEF2 is inactivated by phosphorylation in nucleus in response to neurotoxin, thus leading to neuronal apoptosis. APEX1 AP-endodeoxyribonuclease is repressed by phosphorylation, resulting in accumulation of DNA damage and contributing to neuronal death. NOS3 phosphorylation down regulates NOS3-derived nitrite (NO) levels. SRC phosphorylation mediates its ubiquitin-dependent degradation and thus leads to cytoskeletal reorganization. May regulate endothelial cell migration and angiogenesis via the modulation of lamellipodia formation. Involved in dendritic spine morphogenesis by mediating the EFNA1-EPHA4 signaling. The complex p35/CDK5 participates in the regulation of the circadian clock by modulating the function of CLOCK protein: phosphorylates CLOCK at 'Thr-451' and 'Thr-461' and regulates the transcriptional activity of the CLOCK-BMAL1 heterodimer in association with altered stability and subcellular distribution.
Synonyms: PSSALRE; LIS7
Tractability: Small molecule: a drug acting on it is in phase 2 or 3 trials; a structure with a bound ligand is known; a high-quality ligand is known; it has a binding pocket of medium quality; it belongs to a druggable protein family. Antibody: UniProt places it where antibodies can reach, with high confidence; its Gene Ontology location is reachable by antibodies, with high confidence; the Human Protein Atlas places it where antibodies can reach. PROTAC: it is named in the literature on targeted protein degradation; ubiquitination databases record sites on it; its protein half-life has been measured; a small molecule that binds it is known.
Target class: Kinase; CMGC protein kinase group; Protein Kinase; CMGC protein kinase CDK5 subfamily; CMGC protein kinase CDK family; Enzyme
Chemical probes: GFB-12630 (high quality), GFB-12811 (high quality), TMX-2172 (high quality)
Gene: Protein-coding gene on chromosome 7 (151,051,517 to 151,057,947, reverse strand). Ensembl gene ENSG00000164885.
Subcellular location: Cytoplasm (Isoform 1); Nucleus; Cell membrane; Perikaryon; Cell projection, lamellipodium; Cell projection, growth cone; Postsynaptic density; Synapse; Nucleus (Isoform 2)
Subcellular location (Human Protein Atlas): Nucleoplasm; Plasma membrane; Cell Junctions
Pathways (Reactome):
Gene expression (Transcription): MLL4 and MLL3 complexes regulate expression of PPARG target genes in adipogenesis and hepatic steatosis; NPAS4 regulates expression of target genes
Signal Transduction: Activated NTRK2 signals through CDK5; DARPP-32 events; NGF-stimulated transcription
Circadian clock: Phosphorylation and nuclear translocation of BMAL1 (ARNTL) and CLOCK; Phosphorylation and nuclear translocation of the CRY:PER:kinase complex
Developmental Biology: CRMPs in Sema3A signaling
Disease: Deregulated CDK5 triggers multiple neurodegenerative pathways in Alzheimer's disease models
Hemostasis: Factors involved in megakaryocyte development and platelet production
Gene Ontology:
Molecular function: ionotropic glutamate receptor binding; protein binding; protein serine/threonine kinase activity; signaling receptor inhibitor activity; acetylcholine receptor activator activity; cyclin-dependent protein serine/threonine kinase activity; ErbB-2 class receptor binding; ErbB-3 class receptor binding; kinase activity; microtubule binding; protein kinase activity; tau protein binding; tau-protein kinase activity; ATP binding; Hsp90 protein binding; protein serine kinase activity
Biological process: negative regulation of DNA-templated transcription; negative regulation of proteolysis; oligodendrocyte differentiation; actin cytoskeleton organization; axon extension; axonogenesis; cellular response to amyloid-beta; chemical synaptic transmission; microtubule cytoskeleton organization; negative regulation of calcium ion-dependent exocytosis of neurotransmitter; neuron apoptotic process; neuron differentiation; neuron migration; neuron projection development; positive regulation of neuron apoptotic process; positive regulation of presynaptic cytosolic calcium concentration; regulation of apoptotic process; regulation of cell cycle; regulation of cell cycle phase transition; regulation of dendritic spine morphogenesis; regulation of macroautophagy; regulation of protein localization to plasma membrane; regulation of synaptic plasticity; regulation of synaptic transmission, glutamatergic; regulation of synaptic vesicle recycling; and 5 more
Cellular component: cyclin-dependent protein kinase holoenzyme complex; cytoplasm; nucleoplasm; nucleus; plasma membrane; protein kinase 5 complex; axon; cytosol; dendrite; growth cone; membrane; microtubule; neuromuscular junction; neuron projection; neuronal cell body; postsynaptic density; synapse; filopodium; lamellipodium; perikaryon; presynapse
Genetic constraint (gnomAD): Loss-of-function variants: 17 observed, 43.65 expected, observed/expected ratio (o/e) 0.39, 90% interval 0.27 to 0.58. The upper end of that interval is the gene's LOEUF score, 0.58, which puts it in group 2 of 6, group 1 being the genes least tolerant of losing a copy. Missense variants: 197 observed, 374.82 expected, observed/expected ratio (o/e) 0.53, 90% interval 0.47 to 0.59. Synonymous variants: 143 observed, 157.56 expected, observed/expected ratio (o/e) 0.91, 90% interval 0.79 to 1.04.
Gene-disease validity (ClinGen):
ClinGen rates the evidence that CDK5 causes each of these diseases.
lissencephaly with cerebellar hypoplasia (autosomal recessive): Moderate. Lissencephaly with cerebellar hypoplasia (LCH) is a variant form of lissencephaly and involves a heterogeneous group of cortical malformations without severe congenital microcephaly (>-3 SD).
Homologues: Orthologues: chimpanzee CDK5 (99% identical), dog CDK5 (99% identical), mouse Cdk5 (99% identical), rabbit CDK5 (99% identical), guinea pig CDK5 (99% identical), rat Cdk5 (98% identical), zebrafish cdk5 (97% identical), macaque CDK5 (96% identical), Drosophila melanogaster Cdk5 (78% identical), tropical clawed frog cdk5 (77% identical), Caenorhabditis elegans cdk-2 (48% identical). Paralogues in human: CDK3 (61% identical), CDK2 (59% identical), CDK16 (57% identical), CDK1 (57% identical), CDK17 (56% identical), CDK18 (56% identical), CDK14 (54% identical), CDK15 (52% identical), CDK6 (47% identical), CDK7 (46% identical), CDK4 (45% identical), CDK10 (45% identical), and 14 more.
Diseases named in the same sentence as CDK5 in open-access papers:
CDK5 is named in the same sentence as 265 diseases in open-access papers, as found by Europe PMC text mining. Sharing a sentence is not in itself a finding about the gene and the disease. The quoted sentences say what the papers report.
Alzheimer disease (144 papers, 2006 to 2025). A progressive, neurodegenerative disease characterized by loss of function and death of nerve cells in several areas of the brain leading to loss of cognitive function such as memory and language. "Hyperactivity of cyclin-dependent kinase 5 (Cdk5)/p25 is linked to the production of amyloid and tau pathology in Alzheimer’s disease (AD)." (PMID 39845785, 2024). "Abnormal accumulation of cdk5/p35 in neuronal cell body have been observed in affected brain regions in post-mortem Alzheimer’s disease brains which is consistent with disrupted cdk5/p35 transport caused by loss of LMTK2." (PMID 39520508, 2024). "CDK5 dysregulation has also been associated with multiple neurodegenerative diseases, including Alzheimer’s disease, Parkinson’s disease, and Huntington’s disease." (PMID 37398583, 2023). "Abnormal Cdk5 activity is implicated in several neurodegenerative diseases including Alzheimer’s disease, Parkinson’s disease and Huntington’s disease." (PMID 35421092, 2022). "Cdk5 dysfunction has been implicated in numerous neuronal disorders and neurodegenerative diseases, including Alzheimer’s disease, Parkinson’s disease, amyotrophic lateral sclerosis, prion-related encephalopathies, and Huntington’s disease." (PMID 35383146, 2022). "Hyperactivation of cyclin-dependent kinase 5 (Cdk5) by p25, contributes to neuroinflammation causing neurodegeneration in Parkinson’s disease (PD) and Alzheimer’s disease." (PMID 36351818, 2022). "Cdk5 activity is implicated in various neuropsychiatric and neurodegenerative conditions such as stress, anxiety, depression, addiction, Alzheimer’s disease, and Parkinson’s disease." (PMID 35645825, 2022). "Conversely, Cdk5 activity also serves as a principle feature in excitotoxic signaling and has been implicated in Alzheimer’s disease (AD), Parkinson’s disease (PD), ischemia, and brain injury." (PMID 35645825, 2022). "It has been reported that overactivity of Cdk5 is associated with neurodegenerative diseases such as Alzheimer’s disease (AD), Parkinson’s disease and Huntington’s disease." (PMID 35008611, 2021). "Abnormal regulation of Cdk5 by truncated activators (p25 and p29) contribute to neurodegeneration and has been implicated in Alzheimer’s diseases (AD), amyotrophic lateral sclerosis (ALS), Parkinson’s disease, Niemann–Pick type C disease, and Ischemia." (PMID 31137734, 2019). "Deregulation of Cyclin-dependent kinase 5 (CDK5) by binding to the activated calpain product p25, is associated with the onset of neurodegenerative diseases, such as Alzheimer’s disease (AD)." (PMID 31804596, 2019). "The active p35/CDK5 complex is involved in numerous aspects of brain development and function, and its deregulation is closely associated to Alzheimer’s disease (AD) onset and progression." (PMID 29997370, 2018). "Cyclin-dependent kinase 5 (Cdk5) has been linked to multiple NDDs, including Alzheimer's disease (AD), amyotrophic lateral sclerosis (ALS) and Parkinson's disease (PD)." (PMID 29469033, 2018). "The Cdk5/p25 association is longer and uncontrolled, causing aberrant hyperphosphorylation of various Cdk5 substrates, such as amyloid precursor protein, tau, and neurofilaments, leading to neurodegenerative pathology, including Alzheimer's disease (AD)." (PMID 27283769, 2016). "The pathological characteristics of Alzheimer’s Disease (AD) have been linked to the activity of three particular kinases—Glycogen Synthase Kinase 3β (GSK3β), Cyclin-Dependent Kinase 5 (CDK5) and Extracellular-signal Regulated Kinase 2 (ERK2)." (PMID 24983862, 2014). "It has been reported that hyperactivity of Cdk5 is associated with the neuro-degeneration in Alzheimer’s disease and Parkinson’s disease, and plays an important role in neuronal apoptosis resulted from those stress insults." (PMID 23688022, 2013). "Deregulated activation of cyclin-dependent kinase-5 (Cdk5) is implicated in neurodegenerative disorders such as Alzheimer's disease." (PMID 19534817, 2009).
Alzheimer disease (continued). "As cyclin-dependent kinase 5 (CDK5) has been implicated in the abnormal hyperphosphorylation of tau in Alzheimer's disease (AD) brain, and the development of neurofibrillary tangles, we examined the contribution of this gene to the susceptibility for AD." (PMID 19615060, 2009). "Although Cdk5 activity is necessary for many physiological functions and development of the nervous system, deregulated Cdk5 activity is neurotoxic and has been linked to neurodegenerative diseases such as Alzheimer's disease (AD)." (PMID 19534817, 2009). "Accordingly, proper neuronal function relies upon tight regulation of Cdk5 activity, and alterations in Cdk5 activity are associated with many age-related neurodegenerative diseases, including Alzheimer disease, Parkinson disease, and amyotrophic lateral sclerosis." (PMID 39292114, 2024). "In addition, 5‐LOX overexpression resulted in the activation of cyclin‐dependent kinase 5 (cdk5), which was followed by the significant elevation in the tau phosphorylation rate, which suggests another important mechanism underlying Alzheimer's disease." (PMID 37746665, 2023). "CDK5 and P39 signaling contribute to neuronal network formation, synaptic plasticity, and memory-cognition function; they are especially associated with early-onset Alzheimer’s disease." (PMID 33931731, 2021). "However, disrupted calcium homeostasis in Alzheimer’s disease leads to an aberrant activity of other tau kinases, such as CDK5, causing tau phosphorylation." (PMID 34148071, 2021). "Damage to axonal transport and altered cdk5/p35 are pathogenic features of Alzheimer’s disease." (PMID 31068217, 2019). "Loss of LMTK2 may therefore contribute to Alzheimer’s disease by effects on axonal transport of p35 and cdk5." (PMID 31068217, 2019). "Damage to p35 and disruption of cdk5/p35 activity are strongly linked to Alzheimer’s disease." (PMID 31068217, 2019). "Cyclin-dependent kinase 5 (CDK5) has a major role in CNS development and functioning and its deregulation can contribute to different pathological events implicated in the pathogenesis of Alzheimer’s disease." (PMID 29997370, 2018). "In addition, CDK5 was mainly investigated as an important regulatory gene in the central nervous system (CNS) and as a potential cause of Alzheimer’s disease (AD)." (PMID 29312535, 2017). "Glycogen synthase kinase-3 beta and cyclin-dependent kinase 5 have been identified as being involved in the pathological hyperphosphorylation of tau proteins, which leads to the formation of neurofibrillary tangles and causes Alzheimer's disease." (PMID 28179579, 2017). "However, aberrant activation of Cdk5 is believed to be associated with the pathogenesis of several neurodegenerative diseases, including Alzheimer’s disease (AD) and Parkinson’s disease (PD)." (PMID 25875370, 2015). "The effect of Cdk5 phosphorylation of tau has been studied intensively due to the accumulation of hyperphosphorylated tau in the intracellular tangles that are a hallmark of Alzheimer’s disease." (PMID 25364642, 2012). "Abnormal hyperphosphorylation of Tau, also depending on CDK5 hyperactivation, appears to be the most deleterious step in neurofibrillary degeneration, leading to the formation of neurofibrillary tangles which are associated with Alzheimer's disease." (PMID 21625387, 2011). "CDK5 activity is elevated in several neurodegenerative diseases, particularly Alzheimer’s disease, where this increase is attributed to the accumulation of a truncated form of p35, known as p25." (PMID 40869369, 2025). "In Alzheimer’s disease models, for instance, hyperactivated Cdk5 excessively phosphorylates the protein Tau, leading directly to synaptic damage and cognitive decline, highlighting the critical importance of maintaining a fine balance of Cdk5 activity." (PMID 41369365, 2025).